NPM1P31 (nucleophosmin 1 pseudogene 31)
Gene: Processed pseudogene on chromosome 10 (124,867,510 to 124,868,326, forward strand). Ensembl gene ENSG00000214807.
Diseases named in the same sentence as NPM1P31 in open-access papers:
NPM1P31 is named in the same sentence as 1 disease in open-access papers, as found by Europe PMC text mining. Sharing a sentence is not in itself a finding about the gene and the disease. The quoted sentences say what the papers report.
Huntington disease (1 paper, 2026). Huntington disease (HD) is a rare neurodegenerative disorder of the central nervous system characterized by unwanted choreatic movements, behavioral and psychiatric disturbances and dementia. "In a Huntington’s disease study that analysed human glial progenitor cells transplanted into mice, NPM1P31 was identified as a key DE gene." (PMID 41537925, 2026).